BRCA2 (BRCA2 DNA repair associated)
Diseases named in the same sentence as BRCA2 in open-access papers (continued):
Sharing a sentence is not in itself a finding about the gene and the disease.
endometrial cancer (continued). "In another study, 857 known BRCA1 and BRCA2 carriers aged 45 to 70 were followed over time for the development of endometrial cancer." (PMID 22518164, 2012). "The relationship between BRCA1 and BRCA2 genes mutations and the risk of endometrial cancer is controversial and less clear than the role of BRCA1 and BRCA2 in hereditary breast and ovarian/primary peritoneal cancers." (PMID 22518164, 2012). "Biologically, the coexistence of MSI-H and deleterious DNA damage response (DDR) pathway mutations (BRCA2 and ATM) may drive a hypermutated phenotype, as reported in subsets of colorectal and endometrial cancers." (PMID 41149460, 2025). "The risk of endometrial cancer in women with P/LP BRCA1 or BRCA2 variants is not well characterized." (PMID 39061183, 2024). "Also, germline mutations in genes like BRCA1, BRCA2, and PTEN (associated with Cowden syndrome) contribute to hereditary endometrial cancer risk." (PMID 39296440, 2024). "In addition, PVs in BRCA1, BRCA2, and NBN were significantly associated with moderately increased risks for uterine/endometrial cancer." (PMID 31406321, 2020). "In conclusion, BRCA1 and BRCA2 pathogenic variant carriers do not appear to be at a significant increased risk of endometrial cancer compared with the general population." (PMID 32698099, 2020). "By comparing the clinical and anamnestic characteristics of BRCA2 variants carriers vs. non-carriers, we observed that PanC patients with mutations in BRCA2 were more likely to have a family history for endometrial cancer (50%) compared to the non-carriers (4.3%), p = 0.018." (PMID 36717774, 2023). "There were only two BRCA1 mutation carriers diagnosed with endometrial cancer who were exposed to ET and analyses associated with monotherapy could not be performed in BRCA2 mutation." (PMID 33885953, 2021). "This study, therefore, sought to determine whether BRCA pathogenic variants are associated with an increased risk of endometrial cancer compared with the general population using a large, well-described cohort of BRCA1 and BRCA2 pathogenic variant carriers with prospective follow-ups." (PMID 32698099, 2020). "Thus it seems that screening for endometrial cancer is not warranted in known BRCA1 or BRCA2 mutations carriers." (PMID 22518164, 2012). "Fourteen cases of endometrial cancer were identified in 2609 women (1350 BRCA1 and 1259 BRCA2), of which two were prospectively diagnosed." (PMID 32698099, 2020). "A correlation between BRCA1/2 P/LP variants and endometrial cancer was reported in only five of the 14 studies; such a correlation was related to the BRCA1 variant and not to BRCA2 in two studies." (PMID 39061183, 2024). "However, one of the patients with a BRCA2 gene VUS at c.8417 C > T in our cohort had a family history of leukemia and endometrial carcinoma." (PMID 37277882, 2023). "Some data suggest a slightly increased risk of endometrial cancer in BRCA carriers, with more evidence for a correlation with BRCA1 and then with BRCA2; however, the risk is not clearly defined." (PMID 32655641, 2020). "Of the 4893 women studied, 3536 were BRCA1 pathogenic variant carriers, explaining why there was no statistically significant increase in endometrial cancer risk in the BRCA2 group, despite similar SIRs (BRCA1 SIR = 1.91, 95% CI = 1.06–3.19, p = 0.03, BRCA2 SIR = 1.75, 95% CI = 0.55–4.23, p = 0.2)." (PMID 32698099, 2020).
metastatic disease (42 papers, 2011 to 2026). "This patient also demonstrated loss of the region containing BRCA2 in her primary and metastatic disease." (PMID 41351070, 2025). "Studies have shown that BRCA variant carriers, in particular BRCA2, develop disease at younger ages and have a higher risk of developing metastatic disease and poorer survival." (PMID 40134022, 2025). "This case shows the growing number of ALFs associated with metastatic disease and suggests a possible association between BRCA2 mutation and CRC." (PMID 39156267, 2024). "Genomic sequencing of 11 sites of metastatic disease demonstrated extensive intratumoral heterogeneity, with ten unique BRCA2 reversion mutations across ten sites." (PMID 38355834, 2024). "Multi-gene panel testing figured out another potential treatment strategy using a sample from a distant metastatic tumor and identified a BRCA2 mutation in the tumor." (PMID 37868454, 2023). "The most frequent variant was in BRCA2 (28.57% of all variants), and importantly there was a significant association between genetic variant carrier status and nodal and metastatic disease." (PMID 33486571, 2022). "Somatic BRCA2 mutations have been suggested to arise early in tumors from patients who eventually develop metastatic disease, while ATM alterations seem to enrich in CRPC." (PMID 35740437, 2022). "BRCA2 germline mutations were found in two (16.7%) cases (Patients 1 and 8), one of which showed neuroendocrine features in the primary and metastatic tumors." (PMID 35220606, 2022). "In a study of 2000 patients with localized prostate cancer, including BRCA1 and BRCA2 mutation carriers, 23% of the mutation carriers developed metastatic disease five years after radical treatment." (PMID 34884434, 2021). "We also show that there are hotspots in the structures of ATM and BRCA2 proteins where pathogenic germline, and recurrent somatic variants from primary and metastatic tumours, cluster together in 3D." (PMID 34253785, 2021). "Overall we show that localized castration-sensitive BRCA2-mutant tumours are uniquely aggressive, due to de novo aberration in genes usually associated with metastatic disease, justifying aggressive initial treatment." (PMID 28067867, 2017). "Notably, BRCA2 mutations were significantly enriched in metastatic tumors (9.3% vs. 0%; p = 0.0138), as were SETD2 mutations (11.1% vs. 1.5%; p = 0.0411)." (PMID 39941902, 2025). "They found that BRCA2 mutation carriers were more likely to be diagnosed with high-risk disease (Gleason 8–10), have advanced clinical stage disease (T3/4), and/or have involvement of local lymph nodes or metastatic disease at diagnosis." (PMID 35732815, 2022). "KRAS and BRCA2 mutations were found in both primary and metastatic tumors." (PMID 35666369, 2022). "Men who carry germline variants in BRCA2 with metastatic disease have been shown to have superior responses to PARP inhibition and platinum chemotherapy, signalling the emerging importance of knowing a patient’s variant status, especially if presenting with advanced or metastatic disease." (PMID 33486571, 2022). "However, mutation of KRAS and BRCA2 was found in both primary and metastatic tumors." (PMID 35666369, 2022). "Raw IHC scores, which were the average scores from the quantity and intensity of staining, were plotted for primary and metastatic tumor samples, stratified into WT, BRCA1-mutated and BRCA2-mutated groups." (PMID 38943334, 2024). "-There is emerging evidence that the presence of a mutation in BRCA2, ATM or PALB2 puts the patient at increased risk for biochemical recurrence and metastatic disease." (PMID 35732815, 2022).
metastatic disease (continued). "On the other hand, we documented 3D clusters of pathogenic germline, recurrent somatic variants from primary and metastatic tumours, and hotspots positions in ATM and BRCA2." (PMID 34253785, 2021). "BRCA1 and BRCA2 have been identified as increasingly frequent in advanced metastatic disease compared to primary tumors." (PMID 34884434, 2021). "One of the discrepant tumors in the current cohort (M273), was a metastatic tumor with a germline BRCA2 mutation without inactivity of the other allele." (PMID 35662281, 2022). "TMPRSS2-ETS fusions, and TMPRSS2-ERG fusions specifically, were common in both BRCA2d and BRCA2i, but we did not identify a difference in the frequency of these events by BRCA2 status in either primary or metastatic tumors, as has been reported for germline BRCA2d prostate cancer." (PMID 35715489, 2022). "Intriguingly, while the primary tumors from this patient did not undergo LOH, the metastatic tumors lose the BRCA2 truncating variant, retaining the missense mutated allele." (PMID 34504103, 2021). "In the metastatic disease, BRCA1 was found to be methylated in 26/50 (52%) while BRCA2 was found methylated in 23/50 (46%)." (PMID 38577595, 2024). "BRCA2/ATM carriers were found to have more aggressive features of PrCa at diagnosis: Gleason score 8–10 (88.9% vs 59.5%), metastatic disease at diagnosis (80% vs 52.2%) and higher median PSA at diagnosis (59.0 vs 38.4)." (PMID 39516637, 2024). "Among them, the BRCA1 (chr17q21.31) and BRCA2 (chr13q13.1) loci were frequently amplified (CNV-gain), and most were shared between primary and metastatic tumors." (PMID 36140756, 2022). "Priority genes to test for metastatic disease treatment included BRCA1, BRCA2, and dMMR genes, whereas broader testing such as ATM is reserved for clinical trial eligibility." (PMID 33801751, 2021). "As was observed in primary tumors, no gene differed in high-level amplification frequency by BRCA2 status in metastatic tumors." (PMID 35715489, 2022). "The findings presented here, suggesting that loss of the BRCA2wt allele is a late, rather than early, event in progression toward metastatic disease, have clinical relevance supporting adjuvant, and not single-agent, use of PARP inhibitors in treatment of BRCA2 carriers." (PMID 21958427, 2011).
serous carcinoma (37 papers, 2009 to 2025). "Here, we report a case of a 41-year-old woman diagnosed with high-grade serous carcinoma of ovarian origin and that carried a novel variant in the BRCA2 gene: NM_000059.3:c.(8693_8695delinsGT) p. p.(Leu2898Cysfs*11)." (PMID 40076915, 2025). "Case presentation: An 80-year-old Chinese woman was diagnosed with stage IIIC ovarian high-grade serous adenocarcinoma (CT3cN1MX) with BRCA2 as the causative gene." (PMID 36909189, 2023). "BRCA1 and BRCA2 mutation rates reported as 10% of serous carcinomas earlier, increased up to 40% in recent publications." (PMID 35147976, 2022). "In terms of genetic factors, the role of BRCA1 and BRCA2 mutations as risk factors for serous carcinomas has been established." (PMID 36233495, 2022). "PEO1 is a platinum sensitive (BRCA2-deficient) cell line which was derived from a poorly differentiated serous adenocarcinoma patient who was treated with platinum agents." (PMID 33435622, 2021). "In the first case, a 67-year-old woman with a BRCA2 germline mutation (exon 10 I605fs) had surgery for serous carcinoma of the fallopian tube and received adjuvant chemotherapy." (PMID 33260805, 2020). "For the BRCA2 mutated, the predominant pathology were also the serous adenocarcinoma (50%), followed by one case of peritoneal tumor and one of undifferentiated ovarian tumor." (PMID 27741520, 2016). "The remaining two patients were two sisters (one with clear cell carcinoma and the other with serous carcinoma) who carried the BRCA2 VUS p.S1946P (predicted to be pathogenic by Grantham but classified as benign by SIFT and PolyPhen)." (PMID 27907908, 2016). "CIMBA results confirm that over 70% of OCs in BRCA1 and BRCA2 mutation carriers are grade 3 serous carcinoma." (PMID 25136623, 2014). "Germline BRCA1 and BRCA2 mutations are predominantly associated with high-grade serous carcinoma formation." (PMID 23344037, 2013). "Germ line mutations of BRCA1 or BRCA2 genes predispose primarily to high-grade serous carcinoma of the ovary and approximately 16% of high-grade serous carcinoma is associated with germ line BRCA gene mutation." (PMID 20843305, 2010). "BRCA1 or BRCA2 abnormalities are present in most high grade serous carcinomas and lead to chromosomal instability through loss of the ability to repair double strand breaks by homologous recombination." (PMID 19798417, 2009). "Morphological features of BRCA1 and BRCA2 associated high-grade serous carcinoma." (PMID 33117676, 2020). "Approximately 20%–25% of all high-grade serous carcinoma cases are caused by germline mutations in genes called BReast CAncer gene 1 (BRCA1) and BReast CAncer gene 2 (BRCA2)." (PMID 37519818, 2023). "Approximately 20%–25% of high-grade serous carcinoma cases are caused by germline mutations in the BRCA1 and BRCA2 genes." (PMID 37519818, 2023). "The most common histological subtype was serous carcinoma and BRCA1 mutation appeared to be more frequent compared to BRCA2, as previously reported in the literature." (PMID 36011033, 2022). "BRCA1 (3326A>T) and BRCA2 (1342A>C) mutations were co-existing in patients (II1, II3, and II5) identified as serous adenocarcinoma grade II." (PMID 32356124, 2020). "PEO1 platinum sensitive (BRCA2-deficenent) cell line is derived from a patient with a poorly differentiated serous adenocarcinoma treated with platinum-based drugs." (PMID 35006434, 2020). "High-grade serous carcinomas were by far the most prevalent, and among this group, recurrent variants were reported in both the BRCA1 (c.1674del, c.3331_3334del, and c.5123C>A) and BRCA2 (c.3860del) genes, detected at the germline and/or somatic level." (PMID 40710012, 2025). "The hallmark histopathologic diagnosis of HBOC-related tubo-ovarian cancer due to BRCA mutations is that of high-grade serous carcinoma, and the frequency of BRCA1 and BRCA2 germline mutations increases to approximately 25% in patients diagnosed with these neoplasms." (PMID 33117676, 2020).
serous carcinoma (continued). "Although OCs of patients without a germline BRCA1 or BRCA2 mutation were selected based on their reported serous histology, revision revealed that 13% of these patients did not develop low‐ or high‐grade serous carcinomas (seven out of 54)." (PMID 27767231, 2017). "The sister with serous carcinoma carried a BRCA2 LOH, consistent with the two-hit hypothesis of tumor suppressor gene inactivation." (PMID 27907908, 2016). "Notably, we observed a recurrent BRCA2 variant of uncertain significance (VUS) in two sisters (one with clear cell carcinoma and the other with serous carcinoma)." (PMID 27907908, 2016). "More than half of high grade serous carcinomas overall possess some abnormality of BRCA1 or BRCA2." (PMID 19798417, 2009). "In serous carcinomas, genomic alterations of BRCA1 and BRCA2 accounted for 21.2% (166/784) and 14.7% (115/784) of cases, respectively." (PMID 38201563, 2023). "Analyses of 223 high-grade serous carcinomas uncovered an inverse correlation between AURKA and BRCA2 protein expression, with high AURKA to BRCA2 expression ratios predicting poor survival." (PMID 28881569, 2017). "What is the mechanism underlying genomic instability and development of aneuploidy in ovarian high-grade serous carcinomas that lack BRCA1 and BRCA2 abnormalities?" (PMID 20843305, 2010). "In high-grade serous carcinoma, we observed significant association with longer survival in women harboring BRCA1 or BRCA2 mutation as compared to patients without detectable mutation." (PMID 29587661, 2018). "Exome capture and DNA sequencing of 316 high-grade serous adenocarcinomas, however, did not identify any mutations in RAD51D, although 20% of tumours carried a germline or somatic mutation in BRCA1 or BRCA2." (PMID 22415235, 2012). "Overall, very few differences were observed in the comparisons between high grade serous carcinomas possessing mutation in BRCA1, mutation in BRCA2, epigenetic silencing of BRCA1, and no demonstrable loss in BRCA1." (PMID 19798417, 2009). "Significance analysis of microarrays (SAM) was performed to identify differences in miRNA expression between groups of high grade serous carcinomas with mutations in BRCA1, with mutations in BRCA2, with BRCA1 epigenetic loss and with no demonstrable BRCA1 or BRCA2 loss." (PMID 19798417, 2009).